OLFM4 (olfactomedin 4)
Diseases named in the same sentence as OLFM4 in open-access papers (continued):
Sharing a sentence is not in itself a finding about the gene and the disease.
gastric cancer (continued). "Decreased OLFM4 mRNA inhibit PANC-1 cells proliferation by S to G2/M phase arrest, which is different from our results showing delayed G1 phase progress in gastric cancer." (PMID 22471589, 2012). "Due to limited information on these genes and to a better understanding of common biomarkers associated with cancer of the digestive tract routes, we aim to evaluated expression level of Olfactomedin4 (OLFM4) and (pro)collagen11A1/COL11A1 genes in people with gastric cancer in Iran." (PMID 29511474, 2017). "OLFM4 is secreted and may be detected in serum and plasma therefore representing a good candidate CRC marker as previously suggested for gastric cancer." (PMID 28344541, 2017). "While OLFM4 overexpression has been observed in some cancers, not only of the intestines, but also in lung cancer, gastric cancer and breast cancer 17, others find OLFM4 expressed in differentiated, but not undifferentiated gastric cancer cells." (PMID 26416558, 2015). "Although GREM1, BAG2, OLFM4, TRIP6 and MAGE-A9 have all been previously implicated in tumor progression and metastasis, they have not been linked to intestinal or diffuse subtypes of gastric cancer." (PMID 34885041, 2021). "However, all previous studies were focused on the clinical significance of OLFM4 in all gastric cancer patients regardless of tumor stage, whereas the expression of OLFM4 in EGC and its potential value in predicting LNM of EGC have not been evaluated." (PMID 27294866, 2016).
Sepsis (31 papers, 2016 to 2026). Sepsis is defined as life-threatening organ dysfunction caused by a dysregulated host response to infection. "Indeed, decreased neutrophil CXCR2 expression in sepsis correlates with the Apache II severity score and there is an association between high levels of circulating OLFM4+ neutrophils and mortality." (PMID 37048076, 2023). "OLFM4+ PMN expanded during experimental sepsis and an OLFM4 deficiency ameliorated the disease." (PMID 36922564, 2023). "Furthermore, several studies showed that the abundance of neutrophil subtypes with high expression of OLFM4 was associated with the severity of sepsis." (PMID 36304125, 2022). "Additionally, Higher percentages of OLFM4+ neutrophils were shown to be associated with worsening clinical outcomes in patients with sepsis, blunt traumatic injuries, and ARDS." (PMID 36685531, 2022). "OLFM4 expressing neutrophils have been suggested to be the pathogenic cell type in a murine model of sepsis and in pediatric septic shock and has been trialed along with other neutrophil genes as candidate biomarkers in sepsis." (PMID 32318053, 2020). "Elevated levels of OLFM4+ neutrophils in patients with sepsis are associated with worse outcomes." (PMID 33132754, 2020). "When OLFM4, miR-122-5p, and miR-125b-5p were combined, the AUC for distinguishing between sepsis and septic shock exceeded 0.8." (PMID 39901167, 2025). "Olfactomedin 4 (OLFM4) is produced by a specific group of neutrophils, and increased OLFM4 expression has been linked to worse results in individuals with sepsis and ARDS, influencing the body’s inflammatory reaction after tissue damage." (PMID 39901167, 2025). "The percentage of OLFM4-expressing neutrophils in healthy individuals varies between 8 and 57%, and the levels of positive cells increase in sepsis." (PMID 37048076, 2023). "This is consistent with the findings that OLFM4- neutrophils, in contrast to their OLFM4+ counterparts, provide protection against sepsis-induced mortality in OLFM4-/- mice following LPS stimulation." (PMID 38173719, 2023). "In total, 56% of sepsis patients with elevated OLFM4+ neutrophils died compared to 18% of patients with OLFM4+ neutrophils below 37.6%." (PMID 37048076, 2023). "In healthy individuals, 45–65% of circulating neutrophils express CD177, and 20–25% express the glycoprotein olfactomedin 4 (OLFM4), with the former being increased in abundance in a variety of inflammatory diseases, while the latter is associated with sepsis." (PMID 37386174, 2023). "The number of CD177+ neutrophils, CD64+ neutrophils and OLFM4+ neutrophils is significantly increased in the peripheral blood of patients with sepsis and asthma, which has been confirmed by several studies." (PMID 37492784, 2023). "OLFM4 can be released by neutrophils, and the serum level of OLFM4 is increased in sepsis patients, especially patients with severe disease." (PMID 37048076, 2023). "We have further supported what was found in an experimental mouse model of sepsis, namely that OLFM4 expression colocalizes to the TALH in human kidney tissue, with healthy tissue rarely expressing OLFM4, and injury increasing its expression." (PMID 36117416, 2022). "Concerning the transcripts related to “neutrophil activation,” matrix metalloproteinase 8 (MMP8) showed the highest upregulation in sepsis samples, followed by olfactomedin 4 (OLFM4) and resistin (RETN)." (PMID 36443881, 2022). "OLFM4 null murine pups with sepsis were protected from renal cell apoptosis and plasma creatinine elevation seen in their wild‐type septic counterparts." (PMID 36117416, 2022). "But in cases with overwhelming inflammation and sepsis, OLFM4 switches from the cell-protective role to its predominantly pro-inflammatory role." (PMID 35410162, 2022). "In general, OLFM4 expression is highly increased during inflammatory diseases, such as sepsis, sepsis-induced acute respiratory distress syndrome, and respiratory syncytial virus infection." (PMID 35410162, 2022).
Sepsis (continued). "Our group recently found that wild type murine pups challenged with sepsis showed increased OLFM4 expression that localized to the kidney, specifically to the LOH." (PMID 36117416, 2022). "OLFM4 null mice are protected from death in sepsis models, suggesting its role in the immune response." (PMID 36117416, 2022). "In states of normal health, only about ~25% of human neutrophils express OLFM4; however, it is one of the most upregulated genes in the peripheral blood of patients with sepsis." (PMID 36117416, 2022). "The genes overexpressed in ARDS were often found to be associated with a more severe sepsis outcome in other studies (including MMP8, RETN, and OLFM4)." (PMID 33692779, 2021). "A high percentage of OLFM4+ neutrophils at the time of admission to the intensive care unit also predicts poor outcome in pediatric sepsis patients." (PMID 32470072, 2020). "Increased expression of olfactomedin-4 (OLFM4), a glycoprotein contained within a subpopulation of neutrophils, has been associated with complicated course in sepsis." (PMID 32470072, 2020). "Furthermore, OLFM4 regulates the pro-inflammatory response of lung epithelial cells in sepsis-related ARDS through LDHA-mediated activation of the NF-κB signaling pathway." (PMID 41507134, 2026). "Previous studies have reported that OLFM4 may modulate metabolic disorders to regulate the pro-inflammatory response of lung epithelial cells in sepsis-induced ALI." (PMID 39901167, 2025). "Notably, EV-based panels (miR-122-5p, miR-125b-5p, miR-223-3p, OLFM4, and LCN2) have been found to be associated with the severity or prognosis of sepsis, with promising AUC values." (PMID 39901167, 2025). "Notably, the AUC of multiple markers (0.849) was significantly greater than those of LCN2, OLFM4, and miR-122-5p alone for 28-day mortality in patients with sepsis." (PMID 39901167, 2025). "In hemorrhagic shock and sepsis mouse, inhibition of OLFM4 attenuated lung inflammation in mice." (PMID 37492784, 2023). "Human and mouse neutrophils express OLFM4 phenotype early during cell differentiation and in relation to sepsis, but since its overexpression is correlated with worse outcome, it is suggested that these neutrophils or the OLFM4 secreted may be pathogenic." (PMID 36590595, 2022). "However, it is unclear if these patients always expressed high levels of OLFM4 at baseline, or if sepsis or organ injury induced increased expression of OLFM4." (PMID 32470072, 2020). "Moreover, a new neutrophil-related gene signature has been described in patients with early sepsis-induced ARDS, based on two anti-inflammatory genes: OLFM4 (encoding olfactomedin 4) and LCN2 (encoding lipocalin 2)." (PMID 27807817, 2016). "The data indicated that high expression of miR-122-5p, OLFM4, and LCN2 was associated with a low 28-day survival rate in septic patients with poor prognosis, further suggesting that these miRNAs and proteins in EVs have potential in the diagnosis and prognosis of sepsis." (PMID 39901167, 2025). "Given this renal expression of OLFM4 and association with change in kidney function, we hypothesized that urine OLFM4 (uOLFM4) will be increased in pediatric patients with AKI and sepsis, and that it will localize to the thick ascending LOH (TALH) in pediatric kidney tissue." (PMID 36117416, 2022). "This revealed that OLFM4 expression may be involved with kidney injury in sepsis." (PMID 33863396, 2021). "Our interest in OLFM4 arose when transcriptome analysis demonstrated that OLFM4 was one of the most upregulated genes in pediatric sepsis, and the most upregulated gene in pediatric sepsis with complicated course (defined as death at 28 days or failure of two or more organ systems at 7 days)." (PMID 32470072, 2020). "In septic children, OLFM4, a neutrophil granule protein, promotes RTEC apoptosis; juvenile OLFM4-null mice show sepsis protection, suggesting OLFM4 as a pediatric biomarker." (PMID 41296392, 2025).
Sepsis (continued). "Compared with those in healthy controls, the levels of CD177, SLPI, OLFM4, and LCN2 were elevated in plasma-EVs from patients with sepsis." (PMID 39901167, 2025). "Gene entities exhibiting stronger expression in the SIRS-ranked dataset included CFC1, CT62, lnc-DAAM2-1 and lnc-LTBP3-2 and in the sepsis-ranked dataset included TDRD9, DAAM2, OLFM4 and OLAH." (PMID 38332914, 2023). "Three specific granule genes (OLFM4, LTF, and LCN2) showed <2-fold differences in SIRS vs. presurgical but >10-fold higher levels in sepsis vs. both SIRS and presurgical." (PMID 35844509, 2022). "In conclusion, OLFM4 is elevated in the urine of patients with AKI and sepsis, and there was a correlation between uOLFM4 and NGAL." (PMID 36117416, 2022). "ELANE, MPO, CD177, OLFM4 and OLAH gene expression were found to be comparable in both the groups sepsis and sterile inflammation indicating that neutrophil response to both bacterial infection and tissue injury involved upregulation of these genes." (PMID 34552111, 2021). "In addition, the levels of OLFM4 and LCN2 were greater in patients with septic shock than in those with sepsis." (PMID 39901167, 2025). "A recent study described the increased mortality of sepsis patients with high levels of circulating OLFM4+ neutrophils and the same was true for non-septic patients with infections and Systemic Inflammatory Response Syndrome (SIRS)." (PMID 37048076, 2023). "The role of OLFM4 in gastrointestinal diseases, such as IBD and gastric or colorectal cancer, has been confirmed in a plurality of publications, supporting its influence as sepsis regulator and confirming its survival benefit." (PMID 35410162, 2022). "Thus, the DE genes identified in this study, such as OLFM4, MME, CXCR2,CEACAM8, and ELANE, probably take part in pediatric sepsis development by regulationof neutrophil function." (PMID 33503200, 2021). "We hypothesized that urine OLFM4 (uOLFM4) will be increased in patients with AKI and sepsis." (PMID 36117416, 2022).
colorectal cancer (20 papers, 2013 to 2025). A primary or metastatic malignant neoplasm that affects the colon or rectum. "When tested in a chemically induced colorectal cancer mouse model, loss of OLFM4 in PMN-MDSCs delayed the progression of disease." (PMID 36922564, 2023). "OLFM4, a glycoprotein belonging to the olfactomedin family, is expressed in stem cells located at the base of intestinal crypts and is associated with colorectal cancers through its colocalization with the G-protein-coupled receptor 5 (Lgr5) on columnar stem cells in the crypt base." (PMID 39861713, 2025). "An analysis of the reconstitution process of orgenoids revelaed that OLFM4+ cells in colorectal cancer directrly generate Paneth-like cells, which supported OLFM4+ cells growth by providing niche." (PMID 38182890, 2024). "OLFM4 is overexpressed in various malignancies, including pancreatic cancer, head and neck squamous cell carcinoma, lung cancer, colorectal cancer and breast cancer." (PMID 34885041, 2021). "Other novel potentially targetable TAAs include olfactomedin 4, CD11b, and integrin alpha-2, which were found to be overexpressed in colorectal cancer with liver metastases." (PMID 30804938, 2019). "OLFM4 was also shown to be expressed in the stem cell compartment of the human small intestine, the colon, and a subset of colorectal cancers." (PMID 25254337, 2014). "Thus, determination of OLFM4 in plasma cannot be used as a biomarker for colorectal cancer." (PMID 26416558, 2015). "To further investigate whether the Lgr5+ cells in human GAs had any stem cell properties, we analyzed the levels of ISC markers such as ASCL2, EPHB2, and OLFM4, which are highly expressed in stem-like cells from human colorectal cancers, as well as in murine intestinal adenomas." (PMID 24340024, 2013). "Using patient-derived organoids established from patients with advanced colorectal cancer (CRC), we evaluated the potential of olfactomedin 4 (OLFM4)+ stem cells to produce a bifurcated lineage of progenies with absorptive and secretory properties." (PMID 38182890, 2024). "On the other hand, some studies have suggested that OLFM4-positive gastric and colorectal cancer patients have better survival rates than OLFM4-negative patients." (PMID 31923206, 2020). "We thus conclude that OLFM4 levels in plasma do not reflect OLFM4 expression by colorectal cancers and that OLFM4 identifies a subset of normal individuals with an extremely high level of plasma OLFM4." (PMID 26416558, 2015). "High levels of OLFM4 were found both in normals and in patients with verified colorectal cancer and bare no relation to the presence of cancer." (PMID 26416558, 2015). "Although Olfm4 was not expressed in murine colon, human OLFM4 has been found to be enriched in both small intestinal and colonic crypts, as well as in subsets of colorectal carcinomas." (PMID 25254337, 2014). "However, the level of OLFM4 in plasma has not yet been tested as biomarker for patients diagnosed with primary colorectal cancer." (PMID 26416558, 2015). "Conversely, in human colorectal cancer (CRC), OLFM4 primarily acts as a differentiation marker rather than a direct driver of carcinogenesis or metastasis." (PMID 39861713, 2025).
prostate carcinoma (18 papers, 2012 to 2025). A carcinoma that arises from epithelial cells of the prostate gland. "In fact, in most cancers, a strong association between low OLFM4 and poor tumor differentiation grade was found, including gastric, colon, ovarian and prostate cancer." (PMID 31283789, 2019). "Loss of olfactomedin 4 (OLFM4) gene expression is associated with the progression of human prostate cancer, but its role and the molecular mechanisms involved in this process have not been completely understood." (PMID 26581960, 2015). "Loss of Olfm4 has been associated with progression of prostate cancer and Olfm4 was reported to be a Notch target in intestinal progenitor cells." (PMID 25254337, 2014). "Notably, the prognostic implications of OLFM4 vary by cancer type; for instance, reduced OLFM4 expression correlates with prostate cancer progression, whereas elevated expression is associated with poorer outcomes in pancreatic cancer." (PMID 39861713, 2025). "We also identified putative tumour suppressor OLFM4 to have the highest fold-change in expression (all tumour versus matched benign), an effect recently ascribed to CN loss (19% in our data set) and linked to prostate cancer progression." (PMID 26501111, 2015). "The olfactomedin 4 (OLFM4) gene in humans has been documented to express normally in prostate tissue but reduced in prostate cancer cells." (PMID 35390003, 2022). "Together, these data suggest that olfactomedin 4 plays an important role in the regulation of prostate cancer progression." (PMID 35390003, 2022). "Prostate cancer cells expressing the secreted glycoprotein Olfactomedin 4 (OLFM4) show a reduced bone metastasis due to an inhibited CXCL12-mediated AKT phosphorylation." (PMID 34064589, 2021). "Loss of protein expression of OLFM4 and increased expression of SHH were significantly associated with high grade of prostate cancer." (PMID 26581960, 2015). "Bioinformatic and immunohistochemistry analyses revealed that decreased OLFM4 and increased SHH expression was significantly associated with advanced human prostate cancer." (PMID 26581960, 2015). "Protein expression of the hedgehog signaling-pathway components SHH, PTCH1, GLI1, and GLI2 was also generally reduced in OLFM4-expressing prostate-cancer cells compared with control vector-transfected cells." (PMID 26581960, 2015). "OLFM4 is located on chromosome 13q14.311, which is frequently deleted in many human cancers, including prostate cancer." (PMID 26581960, 2015). "We also obtained more evidence of OLFM4’s ability to inhibit hedgehog-signaling activity in human prostate-cancer cell lines." (PMID 26581960, 2015). "We found that expression of the hedgehog-signaling components SHH, PTCH1, and GLI1 was reduced between 30–70% in OLFM4-expressing prostate-cancer cells compared with control vector-transfected cells." (PMID 26581960, 2015). "We also found that restoration of OLFM4 in human prostate-cancer cells that lack OLFM4 expression significantly downregulated hedgehog signaling-pathway component expression." (PMID 26581960, 2015). "We next studied hedgehog signaling-pathway components in human prostate-cancer cell lines stably expressing the OLFM4 gene." (PMID 26581960, 2015). "Given our results observed in Olfm4-knockout mice and human prostate-cancer cells, we sought to analyze the expression of OLFM4, SHH, and hedgehog signaling-pathway target genes in the GSE3598819 and GDS2545 (GEO profiles) datasets." (PMID 26581960, 2015). "Taken together, our findings suggest that OLFM4 plays a critical role in regulating progression of prostate cancer and might be useful as a novel candidate biomarker for improving diagnostic/prognostic accuracy and as a likely target for therapeutic approaches to prostate cancer." (PMID 26581960, 2015). "In contrast to prostate cancer cells, overexpression of OLFM4 in HL-60 leukemia cells induces their differentiation and apoptosis." (PMID 26561938, 2015).